EREG (epiregulin)
Diseases named in the same sentence as EREG in open-access papers (continued):
Sharing a sentence is not in itself a finding about the gene and the disease.
tumor (continued). "Based on the finding that EREG expression is significantly enhanced in MCF10DCIS compared with MCF10A cells, further studies were performed to determine the contributions of EREG to MCF10DCIS tumor growth." (PMID 26215578, 2015). "While it is possible that the reduction in tumor volume solely reflects an overall decrease in EGF ligand concentration within the tumor, it is also possible that EREG has distinct effects on tumor growth than the other ligands." (PMID 26215578, 2015). "Epiregulin, e.g., is an angiogenic factor that can propagate metastasis by enabling tumor cells to breach lung endothelial barriers and in turn by releasing them into the circulation system." (PMID 25048826, 2014). "Compared to AREG, tumour EREG mRNA expession was a stronger predictor of cetuximab benefit in KRAS wild type cases in three more series." (PMID 23374602, 2013). "The secretory patterns of tumor-primed mononuclear cells are lineage-specific: PBMC co-secrete EREG and OSM, while MΦ co-secrete HB-EGF and OSM." (PMID 23597096, 2013). "We identify HB-EGF and OSM as the key EGFR and STAT3 activators secreted by tumor-primed MΦ, and EREG and OSM as the key activating factors secreted by tumor-primed PBMC." (PMID 23597096, 2013). "In multivariate analysis, favourable predictive factors were high AREG mRNA in KRAS wild type tumours, high EREG mRNA, low Ephrin A2 receptor mRNA." (PMID 23374602, 2013). "Priming by tumor cells upregulated EREG, TGFA and OSM transcripts in PBMC within 24 hrs, as shown by qPCR analysis." (PMID 23597096, 2013). "Culturing of A431 parental tumour cells with Ctx for 48 h remarkably diminished the expression of AREG/EREG proteins to very low or almost undetectable levels." (PMID 22491422, 2012). "AREG and EREG mRNA expression was strongly correlated in both the primary tumor (Rs = 0.81, p < 0.0001) and the liver metastases (Rs = 0.87, p < 0.0001)." (PMID 22409860, 2012). "We are beginning to accumulate evidence that AREG/EREG behave as universal markers for predicting the efficacy of Ctx across most types of EGFR-driven human tumours." (PMID 22491422, 2012). "AREG and EREG mRNA expression from both the primary tumor and liver metastases were measured using real-time RT-PCR." (PMID 22409860, 2012). "This fact indicates that EREG and AREG expression is not only associated with the likelihood of metastasis but is also involved in tumor progression and biological malignancy." (PMID 22409860, 2012). "AREG and EREG mRNA expression was determined in 106 and 105 patients for whom tumour material was available respectively, while PTEN expression was evaluated in 106 patients." (PMID 21283802, 2011). "Amphiregulin and epiregulin are ligands of EGFR and high gene expression is thought to reflect greater dependence of tumor growth on the EGF pathway and thus, greater susceptibility to EGFR inhibition." (PMID 24212785, 2011). "While EREG upregulation in PC tissues could stimulate tumor growth, its silencing inactivates ERK/p38 MAPK pathways, thus inhibiting PDAC." (PMID 41522514, 2026). "Experimental studies have shown that Mtb‐infected macrophages can induce DNA damage and produce epiregulin, which may act as an extracellular survival and growth factor promoting tumor development, especially in squamous metaplasia and tumor formation." (PMID 40347011, 2025). "Epiregulin enhances tumor neovascularization by inducing IL-8, a potent proangiogenic chemokine." (PMID 40724957, 2025). "Finally, all transcriptomic investigations highlighted the constant involvement of epiregulin and ephrin B2, which are involved in cancer progression and tumour cell invasion, respectively." (PMID 39726234, 2025). "Moreover, many of these genes are associated with stemness, such as MUC5B, as well as tumor biology, including REG4, LYZ, EREG, KRT23, and RAMP1, which were also identified in a previous CRC single-cell study." (PMID 39350339, 2024).
tumor (continued). "Our data collectively suggested that EREG plays an important role in the cancer microenvironment under the influence of LPS to increase not only the tumor cell growth and migration/invasion of EGFR-positive HCC cells but also tumor neovascularization via IL-8 signaling." (PMID 38673992, 2024). "EREG and AREG are attractive therapeutic targets for CRC based on their high expression across tumors with different mutational statuses, lower expression in normal tissues, and potential roles in tumor progression." (PMID 40727266, 2024). "Additionally, interaction of tumor-associated macrophages (TAM) and Scissor_C1 via the EREG/EFGR pathway induces tyrosine kinase inhibitor drug-resistance in patients with LAUD." (PMID 37091977, 2023). "Functional experiments showed that EREG knockdown (KD) can significantly inhibit the proliferation detected by Edu exepriments, invasion, migration, and colony forming ability of tumor cells." (PMID 36647156, 2023). "Knockdown of EREG can inhibit the proliferation, invasion, and migration of tumor cells." (PMID 36647156, 2023). "Furthermore, network analysis links these key TF modules to open chromatin regions in genes associated with M2 polarization, tumor growth, and metastasis, including IL-10, TIMP1, and EREG." (PMID 37365178, 2023). "Although higher EREG expression in the tumor foci is correlated with lower survival rate of posttreatment cancer patients, whether blood-borne EREG is technically detectable and can be used as a marker for clinical prediction remains unclear." (PMID 36202915, 2022). "Similarly, miR-215 acts as a tumor suppressor by blocking the EGFR ligand epiregulin, and its transcriptional regulator HOXB9, which was upregulated in hUCMSC-derived exosomes, confirming their tumor suppressor activity." (PMID 35511336, 2022). "Using the cutoff of |logFC|> 1 and the p-value < 0.05, 13,729, 4,718, and 3,817 differentially expressed genes (DEGs) were obtained via differential expression analysis on high and low mRNAsi groups, high and low EREG-mRNAsi groups, tumor and normal groups, respectively." (PMID 35277527, 2022). "Of these, ADM, DCBLD2, EREG, ITGA5, MIF, MMP14, and TREM1 were associated with poor prognosis and significantly increased in tumor, while BTG2 was related to favorable prognosis and decreased in tumor." (PMID 35002712, 2021). "Moreover, tumor-promoting functions were blocked by anti-EREG antibodies or an EGFR-tyrosine kinase inhibitor (EGFR-TKI, gefitinib or erlotinib) in NSCLC." (PMID 34884633, 2021). "The GEPIA database further confirmed the elevated expression levels of EREG in tumor tissues." (PMID 33748108, 2021). "Inhibition of CAT-1 could reduce the survival rate of tumor cells and inhibit the expression of EREG, which was a key factor in the transformation from inflammation to colon cancer." (PMID 34095122, 2021). "Therefore, a comprehensive BCAR1/EREG expression correlation analysis of the TCGA CoAd data set distinguishing tumor localization and stage was conducted." (PMID 34830244, 2021). "EREG promotes tumor progression and metastasis in various cancers." (PMID 34884633, 2021). "Finally, they established significant correlations between high epiregulin expression and primary tumor size and stage, local recurrence, lung metastasis incidence, OS, and metastasis-free survival (MFS)." (PMID 33302367, 2020). "Considering the fact that CSCs were positively correlated with tumorigenesis and radioresistance, samples in TILBSig were ranked based on mRNAsi (tumor stemness index based on mRNA expression) and EREG‐mRNAsi (tumor stemness index based on stem cell epigenetic regulation‐related genes)." (PMID 33098370, 2020). "In addition, Rab27b regulates EREG in response to the IR treatment, and EREG interacts with adjacent cells to promote tumor progression." (PMID 33409495, 2020).
tumor (continued). "Taken together, these results suggest that EREG expression in HNSCC cancer cells could affect their tumor supportive functions and plays a critical role in the oncogenesis of HNSCC, in vitro and in vivo." (PMID 32929368, 2020). "Moreover, the average tumor size and weight of in EREG overexpression group was significantly greater than that observed of the control group (P < 0.05)." (PMID 32929368, 2020). "Then we investigated whether EREG expression in fibroblasts affected their tumor supportive functions." (PMID 31234944, 2019). "On the other hand, NFs demonstrated an in vivo tumor-supportive role after EREG overexpression." (PMID 31234944, 2019). "The effect of AREG and EREG expression levels in primary tumor samples on the outcome of bevacizumab-treated patients is unknown." (PMID 30467535, 2018). "Low levels of expression of AREG and EREG may characterize a tumor that is less dependent on EGFR and, therefore, particularly prone to develop resistance to EGFR inhibitors." (PMID 28002810, 2017). "This phenomenon may result both from the high level of epiregulin expressed in CaSR-WT-transfected cells and the increased tumor burden observed in response to high CaSR activity." (PMID 28915604, 2017). "Additionally, in several tumor cell lines, COX-2 and EREG have been identified as metastasis associated genes." (PMID 28415726, 2017). "Expression of EREG was significantly enhanced, leading to a possible mechanism in which high levels of EREG in the developing tumor microenvironment may enhance tumorigenic properties of the surrounding normal epithelium in a paracrine manner." (PMID 27995036, 2016). "The results from these studies suggest that early stage tumor cells produce increased levels of EREG, and that exogenous EREG is capable of enhancing survival of epithelial cells even in the presence of serum and additional EGF ligand in the context of 3D culture." (PMID 26215578, 2015). "Reduced EREG expression using both shRNA constructs led to a significant reduction in tumor growth." (PMID 26215578, 2015). "AREG was not statistically significant as categorical variable but EREG mRNA at the 75th percentile was associated with a 2.26-fold increased likelihood of tumour response to cetuximab compared to tumours with lower EREG mRNA expression." (PMID 23374602, 2013). "In our series this was the case for AREG, however tumour EREG mRNA retained predictive significance for survival both in KRAS wild-type as well as mutated cases, a counter-intuitive finding, further supported by the predictive significance of EREG for response, even in KRAS mutant patients." (PMID 23374602, 2013). "The autocrine effect of EREG was then examined in a xenograft tumor model." (PMID 24330607, 2013). "AREG and EREG expression showed a modest correlation between primary tumor and liver metastases." (PMID 22409860, 2012). "However, after division by KRAS status, the patients with low EREG expression in the primary tumor had significantly better overall survival than those with high expression in the KRAS wild-type group (p = 0.018, median survival time: 2222 days vs. 1190 days)." (PMID 22409860, 2012). "The positive selection for Ctx-resistant tumour cells exhibiting AREG/EREG cross-suppression may have an important role in the emergence of Ctx resistance." (PMID 22491422, 2012). "Therefore, anti-EGFR antibodies may be effective for the treatment of cancers in which EREG controls tumor growth and drug resistance in an autocrine or paracrine way." (PMID 38398101, 2024). "Although EREG knockout inhibits HCC tumor growth, the molecular mechanisms of EREG remain unclear." (PMID 38673992, 2024). "Interestingly, early-stage tumor cells are able to produce high levels of EREG as well as MMP-1." (PMID 37447165, 2023).
tumor (continued). "Additionally, the tumor suppressor potential of MIAC was recently demonstrated in renal cell carcinoma where MIAC overexpression inhibited tumor growth of renal cancer cells in a subcutaneous xenograft mouse model by inhibiting epiregulin/epidermal growth factor receptor signaling." (PMID 37213226, 2023). "Moreover, AhR is able to increase epiregulin expression and gene transcription, which could play an important role in tumor promotion." (PMID 37447165, 2023). "In addition, treatment with anti-EREG antibodies could effectively combat tumor metastasis when CSCs are abundant in the early stages of cancer development, indicating that targeting EREG may be an option for CSC and drug resistance therapy." (PMID 34884633, 2021). "In addition, a comprehensive strategy that involves monitoring potential biomarkers (e.g., EREG expression) to obtain genomic, proteomic, and immune profiling in tumor tissue, and obtaining liquid biopsy specimens will be helpful for providing tailored therapy." (PMID 34884633, 2021). "However, it is difficult to extrapolate these results to the in vivo setting since EGFR might respond not only to EGF but also to TGF-α, AR, EPGN, BTC, HB-EGF and EREG, which are also increased in tumor tissues." (PMID 31921216, 2019). "Indeed, HSC3 cells coinjected with CAFs demonstrated rapid in vivo tumor growth, but this tumor-supportive effect could be attenuated by EREG knockdown." (PMID 31234944, 2019). "Thus, in addition to overexpression of the EGF receptor, its ligands epidermal growth factor (EGF), transforming growth factor-α TGF-α, amphiregulin (AR), betacellulin (BTC), heparin-binding EGF-like growth factor (HB-EGF), and epiregulin (EREG) have been reported to be upregulated in tumor tissues." (PMID 31921216, 2019). "However, the predictive value of AREG and EREG tumor mRNA levels is currently disputed." (PMID 27344184, 2016). "Tumor cell-secreted factors trigger two stereotype secretory profiles in peripheral blood monocytes and differentiated macrophages: monocytes secrete epiregulin (EREG) and oncostatin-M (OSM), while macrophages secrete heparin-binding EGF-like growth factor (HB-EGF) and OSM." (PMID 23597096, 2013). "Moreover, patients with tumours exhibiting higher EREG or AREG expression had significantly longer PFS, suggesting that these tumours were EGFR dependent and were therefore particularly sensitive to the inhibition of the ligand–receptor interaction by anti-EGFR mAb." (PMID 21139621, 2010). "Notable tumor-associated factors that appear to be highly expressed only in the Lewis lung cancer cell line that are also known to be involved in cancer, are osteopontin, kit ligand (stem cell factor), chemokine (CXC) ligand 1, pleiotropin, fibroblast growth factor 7, amphiregulin and epiregulin." (PMID 18489769, 2008). "TPST1-high tumor cells exhibited proliferative enrichment and potential interaction with myeloid cells via PTN-NCL and EREG/AREG-EGFR signaling pathways." (PMID 41838327, 2026). "This invGRN comprises fDEGs and is activated by subtypes of EGFR-activity that are primarily governed by EGFR ligands AREG, EREG, and HBEGF in single tumor cells." (PMID 40121428, 2025). "EREG, an EGFR ligand upregulated in CRC and intestinal stem cell niches, contributes to tumor progression and metabolic adaptation." (PMID 40463370, 2025). "Additionally, our recent study suggested that epiregulin facilitates cellular communication between HCC cells and activated HSCs, thereby promoting the progression of HCC by enhancing cancer cell proliferation, migration, invasion, and tumor angiogenesis caused by LPS stimulation." (PMID 40724957, 2025). "C12orf56 was expressed at higher levels in normal samples, whereas EREG and INHBB were expressed at higher levels in tumor samples." (PMID 39883700, 2025). "Recent studies have highlighted the role of EREG in the regulation of the EMT, angiogenesis, cancer stemness, and immune evasion in the tumor microenvironment." (PMID 38398101, 2024).
tumor (continued). "Our findings indicate that HDCA suppresses the EREG/EGFR signaling route by activating FXR, thereby hindering the growth of CRC cells and demonstrating a tumor-inhibiting effect in CRC." (PMID 39834394, 2024). "Elevated EREG mainly activates EGFR signaling pathways and promotes tumor progression in HNSCC cells." (PMID 38945975, 2024). "The TGF-β ligand is a key inducer of the EMT, and TGF-β signaling in the tumor microenvironment enhances cell proliferation and angiogenesis by activating the HB-EGF/IL-1β/EREG pathways." (PMID 38398101, 2024). "MAbs and ADCs targeting EREG and AREG are in preclinical development and have thus far demonstrated to be well-tolerated while achieving TGI in variety of tumor models, including CRC." (PMID 40727266, 2024). "C1Qhigh TAMs interact principally with aDTCs via the epiregulin-epidermal growth factor receptor (EGFR) and CD226-NECTIN2 receptor–ligand pairs, which are involved in tumor-cell survival and proliferation." (PMID 38460015, 2024). "Taken together, these data show that the concomitant silencing of EREG and EGFR targeting would be more effective in inhibiting tumor growth and survival." (PMID 36899869, 2023). "EREG demonstrated higher RNA expression in NSCLC than in normal lung epithelial cells, while there was little difference in ADH1C between normal and tumor lung cells, which needs additional experiments for validation." (PMID 37077811, 2023). "Epiregulin (EREG) is a ligand of epidermal growth factor receptor (EGFR), which is involved in RAS-RAF-MAPK and PI3K-AKT-mTOR signaling pathways regulating tumor proliferation, invasion, and migration." (PMID 36874096, 2023). "In NSCLC, EREG reduces TKI-induced apoptosis through the EGFR/ERBB2 and AKT signaling pathways, thereby contributing to TKI resistance in tumor cells." (PMID 37091977, 2023). "These monocytes and macrophages in luminal tumor hubs upregulate inflammation (MMP12 and MMP9), myeloid cell recruitment (CCL2 and CCL7), and tumor growth–promoting genes (VEGF and EREG)." (PMID 37492581, 2023). "The obtained mouse tumor cells were subjected to RT-qPCR to examine the expressions of CYP4A22-AS1, EREG, and BCL-2." (PMID 37670265, 2023). "Further mechanistic studies have demonstrated that MIAC directly bind to AQP2 protein, inhibit EREG/EGFR expression and activate downstream pathways PI3K/AKT and MAPK to achieve anti-tumor effects." (PMID 36117171, 2022). "In the tumor tissues of NSCLC patients, 64.7% of tumors were EREG positive as shown by IHC staining." (PMID 35551652, 2022). "We recently showed that EREG is upregulated in CAFs from OSCC patients, with elevated expression correlating with the tumor severity and predicted shorter overall survival." (PMID 35844493, 2022). "Taken together, this suggests that EREG signaling at least in part contributes to the activation of the oncogenic STAT3 and ERK1/2 signaling pathways in Phd2+/– tumor cells in CAC." (PMID 36509284, 2022). "Mechanistically, EREG appeared to be essential for normal fibroblast to CAF transformation and essential for the induction of tumor cell EMT in a JAK2-STAT3- and IL-6-dependent manner." (PMID 35844493, 2022). "Therefore, autocrine and paracrine EREG overexpression in distinct cells may synergistically activate different signaling cascades, miRNA, and aerobic glycolysis pathways that promote primary tumor growth, metastasis, and drug resistance in the TME." (PMID 34884633, 2021). "Exposure to airborne contaminants, such as polycyclic aromatic hydrocarbons, can upregulate EREG expression through the EGFR signaling pathway, thereby promoting tumor progression." (PMID 34884633, 2021). "Treatment with the small-molecule EGFR inhibitor gefitinib suppressed EREG/EGFR downstream signaling pathways and reduced tumor formation in xenograft animals bearing EREG-overexpressing GBM cells." (PMID 34884633, 2021).